BRAF (B-Raf proto-oncogene, serine/threonine kinase)
Diseases named in the same sentence as BRAF in open-access papers (continued):
Sharing a sentence is not in itself a finding about the gene and the disease.
melanoma (continued). "To identify small molecules that can inhibit the viability of thyroid cancer cells, we developed a screening platform using 8505C and KTC-1 cells that harbor the BRAFV600E mutation and, as a reference for a non-thyroidal BRAF mutant phenotype, human melanoma Malme-3M cells." (PMID 26942566, 2016). "VEM can induce rapid and substantial responses in approximately 50 % of patients with advanced, BRAF-mutated melanoma, but in most cases responses are not durable, as tumors develop resistance to BRAF inhibition due to activation of alternate signaling pathways." (PMID 27532019, 2016). "Furthermore, approximately 1 in 5 patients with BRAF mutant melanoma shows progression at first assessment during treatment, due to intrinsic/primary resistance in their tumors indicating that the mutational status of the target oncogene is insufficient to predict responsiveness to therapy." (PMID 25742786, 2015). "In melanoma, identification of activating mutations in BRAF as the major cause of constitutive activation of the mitogen activated protein kinase (MAPK) pathway has led to successful development of mutant BRAF-specific inhibitors in the treatment of the disease." (PMID 26573229, 2015). "Moreover, NRP-1-dependent pathways described in endothelial cells or other tumor models might be active in melanoma and contribute to BRAF inhibitor resistance." (PMID 26090340, 2015). "Given that some BRAF-mutant melanoma patients fail to respond to BRAF inhibitors, and that the majority of patients who do respond to BRAF/MEK inhibitors eventually develop resistance, there is an urgent need to identify possible combination treatments that may be effective." (PMID 25886620, 2015). "Therefore, continued dependence on the Bim/VDAC1 pathway may be an important contributor to BRAF inhibitor-resistant melanoma." (PMID 26462148, 2015). "Therefore, targeting SOCE could be a new strategy to treat a great number of melanoma patients, in monotherapy or in combination with BRAF inhibitors." (PMID 25710007, 2015). "Interestingly, two ongoing clinical studies are currently analyzing the kinetics and effects of BRAF inhibition with vemurafenib (960 mg BID) on the innate and adaptive immune system in patients with unresectable melanoma expressing a BRAFV600 mutation (NCT01942993 and NCT01813214)." (PMID 25709607, 2015). "Thus quantitative, rather than qualitative, evaluation of BRAF mutation deserves to be considered as a standard item in reporting the mutational status of melanoma." (PMID 26141748, 2015). "Importantly, zoledronic acid could inhibit clonogenic growth in the majority of melanoma cell lines except in the three BRAF mutant but PTEN wild-type melanoma lines." (PMID 25646931, 2015). "Since NRAS mutations are found in 18% of MM and are furthermore observed as an escape mechanism against first-line vemurafenib treatment in BRAF-mutant MM, MEK-inhibition could represent a promising therapeutic target to enhance the susceptibility of melanoma cells to therapy-induced DNA damage." (PMID 26136337, 2015). "Moreover, in melanomas, PTEN gene loss generally co-exists with the activation of BRAF mutations." (PMID 26393652, 2015). "Oncogenic BRAF (but not wildtype BRAF), which is mutated in up to 50% of melanomas, also regulates MITF via simultaneously stimulating MITF activation through ERK phosphorylation, which leads to its subsequent degradation, and by inducing transcription of MITF via BRN2 upregulation." (PMID 25755924, 2015). "Therefore, it can be hypothesized that a therapeutic advantage is achieved in BRAF mutant melanoma tumors by first blocking OXPHOS and adaptation to hypoxia with BAY 87-2243, followed by subsequent downregulating of glycolysis using vemurafenib." (PMID 26500770, 2015). "However, the demonstration that BRAF is even mutated in common nevi suggests that its oncogenic activation is necessary, but not sufficient, for the development of melanoma." (PMID 26322273, 2015).
melanoma (continued). "It is of critical importance to identify therapies which could have potential application in patients with BRAF mutation-negative melanomas and for patients that have failed initial therapy with BRAF inhibitors." (PMID 25915038, 2015). "However, melanoma patients frequently develop resistance to BRAF inhibition." (PMID 25600636, 2015). "Interestingly, we also found that a subgroup of intrinsically resistant melanoma cells (that have a loss of PTEN), were capable of secreting their own fibronectin in response to a number of cellular stresses including BRAF inhibitor therapy, chemotherapy, and changes in pH." (PMID 26622938, 2015). "In addition, Xu and colleagues performed a PB screen in melanoma cells and identified BRAF and CRAF as mediators of resistance to the BRAF inhibitor vemurafenib, recapitulating previous observations in human melanoma patients and cell lines treated with vemurafenib." (PMID 26481584, 2015). "Based on the results of our in vitro and in vivo growth inhibition studies, we hypothesized that a synergistic reduction in cell growth and induction of apoptosis with fisetin and sorafenib in BRAF-mutant melanoma cells might also abrogate growth of established tumors." (PMID 26299806, 2015). "BRAF mutations may be detected in archived formalin-fixed, paraffin-embedded (FFPE) melanoma tissue; however, it is currently unclear whether primary tumors, consecutive metastases, or both should be preferentially analyzed because of the possibility of intertumor heterogeneity." (PMID 26498143, 2015). "As quantification of genomic DNA obtained from FFPE samples may not be representative of BRAF mutated messenger RNA (mRNA), we extracted both mRNA and genomic DNA (gDNA) from 27 frozen melanoma samples." (PMID 26141748, 2015). "In melanoma, the quantity of tumor associated mutant BRAF ctDNA correlated with tumor burden, and lower concentrations of basal mutant BRAF ctDNA were associated with a higher overall response rate and longer progression-free survival (PFS) in patients treated with BRAF inhibitors." (PMID 26524482, 2015). "However, to the best of our knowledge, the effect of melanin content in the detection of BRAF mutation in melanoma sample has never been addressed before." (PMID 26690267, 2015). "However, recent evidence indicates that melanomas bearing mutant BRAF may also have altered immune responses, suggesting additional avenues for treatment of this patient group." (PMID 26605342, 2015). "However, targeting HRAS might be limited by development of resistance as seen for BRAF inhibitors in melanoma." (PMID 26544513, 2015). "BRAF mutants with impaired or unknown kinase activity as well as concomitant kinase-impaired BRAF mutations and RAS mutations were detected in lung cancers, colorectal cancers and melanomas." (PMID 26498038, 2015). "Here, we have further shown that increased expression of BRAF protein (regardless of the mutation status) in Stage I melanoma is a significant prognostic marker, in that the higher the BRAF expression the more likely the patient will experience a worse outcome." (PMID 25784655, 2015). "Finally we showed that, as opposed to melanomas, benign melanocytic tumors with BRAF mutations did not have any chromosome 7 instability." (PMID 26141748, 2015).
melanoma (continued). "Moreover, that same study showed that Nodal expression was not affected in melanoma cells expressing a BRAF mutation when treated with a BRAFi." (PMID 26460952, 2015). "Taken together, these data suggest that the EZH2 GOF mutations may not drive intrinsic melanoma cell proliferation (as do mutations in driver genes like BRAF), but rather function by shaping the interactions between melanoma cells and their microenvironment." (PMID 25671303, 2015). "Thus, the BRAF mutational status does not play a major role in directly determining the efficiency of PD-1 pathway blockade in melanoma cells." (PMID 26305724, 2015). "In addition, similar to the results obtained using the TCGA cohort, the proliferative versus invasive split is not correlated with any specific mutations in known melanoma driver genes, such as BRAF." (PMID 25865119, 2015). "Non-p.V600E codon 600 mutations were seen in 8 of 68 (12 %) BRAF-mutated melanomas." (PMID 26498038, 2015). "Compared to tumors without the mutation, the P131L mutant positive tumors were associated with increased thickness (p = 0.02), head and neck (p = 0.009) and upper limb (p = 0.03) location, lentigo maligna melanoma subtype (p = 0.02) and BRAF V600K (p = 0.04) but not V600E or NRAS codon 61 mutations." (PMID 25544760, 2015). "However, whether the expression of endosialin is upregulated in BRAF inhibitor –resistant melanoma is interesting and remains to be determined." (PMID 26085332, 2015). "However, less than half of melanomas harbor this mutation, and consequently, do not respond to the current BRAF targeted treatments." (PMID 25798946, 2015). "Furthermore, systemic therapy is also rapidly evolving for melanoma, and it is possible that newer agents (e.g., immune checkpoint and BRAF inhibitors) could become part of standard treatment in the future." (PMID 26626714, 2015). "As both N-RAS and BRAF are upstream of mitogen-activated protein kinases-extracellular signal regulated kinases (MAPK-ERK) pathways, somatic mutations in these genes result in constitutive activation of ERK signaling, which is considered as integral pathway in melanoma development." (PMID 26393652, 2015). "However, recently, combinations targeting the same pathway (e.g. trametanib (MEK) inhibitor together with dabrafenib (BRAF inhibitor) in BRAF-mutant melanoma or resistance pathways (combining PIK3CA and MEK inhibitors) showed efficacy, either preclinically and/or in the clinic." (PMID 25944621, 2015). "Trametinib could safely be given with weekly paclitaxel at the full monotherapy dose with promising progression free and overall survival in the phase I trial in patients with melanoma lacking a V600 BRAF mutation." (PMID 25915534, 2015). "However, melanoma can progress from RGP to VGP in the absence of this mutation (i.e. wild-type BRAF), suggesting that this mutation is not the only factor mediating melanoma invasion and metastasis." (PMID 25798946, 2015). "Melanomas that arise from mucosal and acral sites are unlikely to present with BRAF mutations." (PMID 26705496, 2015). "As exemplified by trials for BRAF V600E metastatic melanoma, treatment with dabrafenib monotherapy versus the combination of dabrafenib and trametinib in BRAF V600E mutated melanoma can significantly improve overall survival without increasing overall toxicities." (PMID 26062823, 2015). "However, compensatory signaling through the RAS/RAF/MEK/ERK pathway following tyrosine kinase receptor upregulation or pathway cross-talk can lead to resistance to PI3K inhibitors, particularly in BRAF-mutant melanoma where ERK signaling is enhanced, warranting the need for combination therapy." (PMID 26137449, 2015). "However, the protein expression profiles and the precise prognostic value of BRAF in melanoma remain largely unknown." (PMID 25784655, 2015).
melanoma (continued). "Thus, inhibition of NRP-1 may prevent the activation of compensatory mechanisms that stimulate melanoma cell proliferation and limit the efficacy of BRAF inhibitors." (PMID 26090340, 2015). "Notably, our findings that COX-2 expression depends on active RAF/MEK signaling suggests that reduced production of PGE2 by melanoma cells may contribute to the immune-dependent anti-cancer activity elicited by BRAF inhibitors." (PMID 26343581, 2015). "Also, metformin, in combination with BRAF inhibitors, has been shown to suppress melanoma growth." (PMID 26484566, 2015). "Loss of PTEN, which is observed in 10-33% of melanoma specimens, may contribute to intrinsic resistance to BRAFi via increased PI3K/AKT signaling when BRAF is inhibited and suppression of apoptosis mediated by proapoptotic protein BIM, member of the Bcl-2 protein family." (PMID 25344914, 2014). "Among which, mutationally activated BRAF has been identified in a variety of cancers recently and it occurs in a non-overlapping occurrence in many cancers such as melanomas, colorectal carcinomas, papillary thyroid carcinomas, serous ovarian carcinomas and lung cancers." (PMID 24967732, 2014). "We found that the ERK pathway is constitutively activated in Grey horse melanoma tumours and cell lines in the absence of somatic activating mutations in BRAF, RAS, GNAQ, GNA11 and KIT genes or alterations in the expression of the main components of the pathway." (PMID 25413220, 2014). "In addition to anti-thyroid effects seen with treatment of the specific RAF inhibitor PLX4032 in BRAF-mutated cancer cells, we observed paradoxical activation of the MAPK pathway in BRAF-wild-type Nthy-ori 3–1 thyroid cells, as previously seen in BRAF-wild-type melanoma cells." (PMID 24673746, 2014). "RAC1 is a RAS-related GTPase that regulates cell proliferation and migration; RAC1P29S is a recurrent UV-signature mutation in cutaneous non-acral melanomas and was the third most frequent activating mutation (9.2%) after those of BRAF and NRAS in a large cohort (n=147) of exome-sequenced melanomas." (PMID 25344914, 2014). "We found that the ERK pathway is constitutively activated in Grey horse melanoma tumours and cells in the absence of somatic oncogenic mutations in BRAF, RAS, GNAQ, GNA11 and KIT that are associated with activation of this pathway in the majority of human melanocytic tumours." (PMID 25413220, 2014). "Taken together, these data provide preliminary in vitro evidence that SCH772984 may more potently and more durably inhibit BRAF-mutant melanoma compared to single agent vemurafenib, and that the combination of BRAF and ERK inhibition results in better inhibition than either alone." (PMID 25142146, 2014). "Therefore, we analyzed the efficacy of MI-181 in a panel of melanoma cell lines with defined genetic backgrounds including BRAFV600E and NRASQ61L mutations and varied sensitivities to Vemurafenib (BRAF inhibitor) and Trametinib (MEK inhibitor), which are currently used to treat BRAFV600E melanomas." (PMID 25321469, 2014). "Importantly, TREVA has been successful in the molecular subtyping of melanomas, which may direct novel therapeutic options for BRAF/NRAS wild-type patients." (PMID 24752294, 2014). "Therefore, ERK inhibitors hold much promise to augment the armamentarium of effective targeted therapies for melanoma, regardless of BRAF mutational status and irrespective of sensitivity to BRAF inhibitors." (PMID 25142146, 2014). "Quantitation of p-S6 could serve as a biomarker to guide treatment of BRAF mutant melanoma." (PMID 24743024, 2014). "Therefore, BRAF mutations must not be disregarded in oral malignant melanoma, underlining the importance of the molecular analysis of BRAF mutations for patients affected by this rare disease subtype." (PMID 25120707, 2014).
melanoma (continued). "One study has indicated that the presence of a BRAF mutation markedly correlates with inferior survival in a metastatic setting, however, this finding was not paralleled by differences in disease-free survival (DFS) from the time of the primary melanoma diagnosis." (PMID 24959217, 2014). "Finally another recent report suggests XPO1 inhibitors may synergize with BRAF inhibitors to elicit antitumor effects against melanoma." (PMID 25057921, 2014). "In addition, in melanoma, it appears that oncogenic BRAF-signaling may cloak immune antigens present on the cancer cells and that treating with BRAFV600E-inhibitors promotes anti-tumor immune cell infiltration and activity." (PMID 24994118, 2014). "Thus, the autophagy flux is constitutively activated at low levels in melanoma cells irrespective of their BRAF mutational status." (PMID 25365078, 2014). "Here, we treated two melanoma brain metastasis cell lines, H1_DL2, harboring a BRAFV600E mutation and PTEN loss, and H3, harboring WT (wild-type) BRAF and PTEN loss, with the MAPK (BRAF) inhibitor vemurafenib and the PI3K pathway associated mTOR inhibitor temsirolimus." (PMID 24840574, 2014). "This is evidenced by the successful targeting of BRAF mutation (V600E)-associated melanoma with BRAF and downstream MEK inhibitors, but the lack of efficacy in BRAF-mutated colorectal cancer, perhaps due to more genomic alterations and resultant bypass pathways." (PMID 25286031, 2014). "Indeed, new mutations are being discovered, such as recent identification of BRAF fusions in 4-8% of melanomas without mutations in the known “drivers”." (PMID 24743024, 2014). "At this dose level,an overall response rate was seen in 69% of BRAF V600E-mutated melanoma (36 patients) and 78% of BRAFV600K-mutated melanoma (27 patients), confirmed in 50% and 56%, respectively.Median relapse-free survival of 5.5 months was seen in patients with a BRAF mutation." (PMID 25089220, 2014). "In the current study, which represents the largest analysis of the prognostic impact of BRAF mutations in non-metastasized melanoma patients thus far, we retrospectively analyzed the BRAF status in patients who had not been selected on the basis of their later disease course or outcome." (PMID 24475086, 2014). "40-60% melanoma patients carry BRAF mutations that activate MAPK signaling and this association could have therapeutic implications for the treatment of patients with BRAF mutant melanoma." (PMID 24884660, 2014). "However, the interference of CRAF in melanoma cells harboring the BRAF V600E mutation did not significantly alter their biological properties." (PMID 25422890, 2014). "Since rapid development of resistance (within hours) through up-regulation of MEK pathway signaling in the absence of BRAF mutations has been reported in melanoma cell lines, we have also measured in some cell lines the time-dependent effects of CI-1040 and vemurafenib on ERK phosphorylation." (PMID 23658559, 2013). "Finally, patients with MC1R variants had a 5- to 15-fold increased risk of BRAF-mutant melanomas regardless of signs of chronic solar damage." (PMID 24416617, 2013). "Interestingly, the most common mutations found in melanomas, in BRAF and NRAS, do not occur as a result of UV-irradiation." (PMID 23303275, 2013). "The highest rate of BRAF mutation was observed in non-chronic sun-induced damage melanoma but almost all histological subtypes of melanoma may exhibit such mutation making it an attractive candidate for targeted therapy at advanced or metastatic stages." (PMID 23976959, 2013). "Could therapies targeting BRAF be successfully used to treat earlier stages of melanoma?" (PMID 24381933, 2013). "Furthermore, melanomas on skin that have not been chronically exposed to sun usually carry either a mutated NRAS or mutated BRAF (somatic mutations in such genes have been reported as mutually exclusive)." (PMID 23987572, 2013).